SCRG1 (stimulator of chondrogenesis 1)
Synonyms: ScRG-1; lincSCRG1
Tractability: Antibody: UniProt places it where antibodies can reach, with high confidence; UniProt predicts a signal peptide or a membrane-spanning region; its Gene Ontology location is reachable by antibodies, with medium confidence.
Gene: Protein-coding gene on chromosome 4 (173,384,701 to 173,410,218, reverse strand). Ensembl gene ENSG00000164106.
Subcellular location: Secreted
Gene Ontology:
Molecular function: protein binding
Biological process: nervous system development
Cellular component: extracellular region; Golgi apparatus; neuron projection terminus; cytoplasm
Genetic constraint (gnomAD): Loss-of-function variants: 3 observed, 6.32 expected, observed/expected ratio (o/e) 0.47, 90% interval 0.22 to 1.22. That is too few expected variants to judge how well the gene tolerates losing a copy. Missense variants: 87 observed, 101.51 expected, observed/expected ratio (o/e) 0.86, 90% interval 0.72 to 1.02. Synonymous variants: 40 observed, 36.16 expected, observed/expected ratio (o/e) 1.11, 90% interval 0.86 to 1.44.
Homologues: Orthologues: chimpanzee SCRG1 (100% identical), macaque SCRG1 (94% identical), pig SCRG1 (92% identical), rabbit SCRG1 (88% identical), dog SCRG1 (87% identical), mouse Scrg1 (82% identical), rat Scrg1 (81% identical), guinea pig SCRG1 (79% identical), tropical clawed frog scrg1 (62% identical).
Diseases named in the same sentence as SCRG1 in open-access papers:
SCRG1 is named in the same sentence as 23 diseases in open-access papers, as found by Europe PMC text mining. Sharing a sentence is not in itself a finding about the gene and the disease. The quoted sentences say what the papers report.
scrapie (5 papers, 2015 to 2025). A fatal disease of the nervous system in sheep and goats, characterized by pruritus, debility, and locomotor incoordination. "Transcripts of SCRG1 (scrapie-responsive gene 1), whose encoded protein has been linked to the presence of autophagic vacuoles in neurons of scrapie-infected mice at terminal stage, are also enhanced in sporadic CJD (sCJD) and murine models of scrapie and BSE." (PMID 32984276, 2020). "In addition, ultrastructural localization of scrapie-responsive gene 1 (Scrg1) protein was associated with AVs in the central neurons of scrapie-infected mice." (PMID 36674920, 2023).
transmissible spongiform encephalopathies (5 papers, 2020 to 2025). "A protein called SCRG1 is involved in autophagy and has been linked toneurodegeneration in transmissible spongiform encephalopathies and brain damage." (PMID 40129438, 2025). "For example, SCRG1 (Scrapie Responsive Gene 1) is involved in neurodegeneration and autophagy and is associated with transmissible spongiform encephalopathy." (PMID 34781885, 2021). "SCRG1 is a small protein with a length of 98 amino acids, rich in cysteine, is mainly distributed in the central nervous system, and was discovered through the identification of the genes associated with the neurodegenerative changes observed in transmissible spongiform encephalopathies." (PMID 35720295, 2022). "Scrg1 mRNA produces a small secreted-peptide up-regulated in transmissible spongiform encephalopathies." (PMID 32295841, 2020).
liver fibrosis (3 papers, 2020 to 2021). "Linc-SCRG1 (a lncRNA with a transcript length of 3118 bp) is expressed in only humans and specifically combines with increased tristetraprolin (TTP) protein levels during liver fibrosis progression in activated LX2 cells induced by TGF-β and in human tissues." (PMID 32098245, 2020).
osteoarthritis (3 papers, 2022 to 2025). A noninflammatory degenerative joint disease occurring chiefly in older persons, characterized by degeneration of the articular cartilage, hypertrophy of bone at the margins and changes in the synovial membrane. "In conclusion, SCRG1, as a diagnostic marker of osteoarthritis, co-regulates immune-related pathways through the interaction of related proteins, playing an important role in the occurrence and development of osteoarthritis, which may be a novel drug target." (PMID 35720295, 2022). "The classification model constructed by LASSO analysis showed that six genes including CDKN1A, FOSB, STMN2, SLC2A3, TAC, and SCRG1 can be used as biomarkers of osteoarthritis, and the SCRG1 gene shows importance in osteoarthritis." (PMID 35720295, 2022).
Alzheimer disease (1 paper, 2011). A progressive, neurodegenerative disease characterized by loss of function and death of nerve cells in several areas of the brain leading to loss of cognitive function such as memory and language. "Novel candidates are associated with neurodegenerative disorders including Alzheimer's disease (VSNL1), prion disease (SCRG1, HSPH1, HSPA5 and CTR9) and age-related degeneration (GAS6 and GNG11)." (PMID 21569303, 2011).
atherosclerosis (1 paper, 2025). A disease characterized by the build-up of fatty material and calcium deposition in the arterial wall resulting in partial or complete occlusion of the arterial lumen. "SCRG1 is identified as one of the critical diagnostic markers involved in infiltration of immune cells in atherosclerosis." (PMID 40362725, 2025).
bipolar disorder (1 paper, 2014). A disorder of the brain that causes unusual shifts in mood, energy, activity levels and the ability to carry out day-to-day tasks. "While no gene is presently linked to ID in this region, the gene SCRG1 is highly expressed in the brain and has differential regulation in schizophrenia and bipolar disorder." (PMID 24962056, 2014).
breast carcinoma (1 paper, 2022). "SCRG1 is also specifically highly expressed in breast cancer with metastatic propensity and might serve as an ideal indicator for developmental cancer-associated fibroblasts." (PMID 36241983, 2022).
gastric cancer (1 paper, 2022). A primary or metastatic malignant neoplasm involving the stomach. "Except for SCRG1 and THBS4, the other hub genes were expressed at lower levels in the gastric cancer tissues than in the normal tissues." (PMID 35392086, 2022).
lymph node metastasis (1 paper, 2022). "The upregulation of SCRG1 was previously reported in STAD with lymph node metastasis in a data-mining study; however, the mechanism was not explained." (PMID 36241983, 2022).
pneumonitis (1 paper, 2022). An inflammatory process affecting the lung parenchyma. "Several of these filtered candidates were found to be secreted (C12orf49, COL10A1, FNDC4, ITLN2, MATN3, PDZD2, RS1, SCRG1, and ST6GALNAC5) making them potential candidate biomarkers useful for distinguishing IPF from pneumonitis." (PMID 35628257, 2022).
pulmonary fibrosis (1 paper, 2022). Chronic progressive interstitial lung disorder characterized by the replacement of the lung tissue by connective tissue, leading to progressive dyspnea, respiratory failure, or right heart failure. "The role of crapie responsive gene 1 (SCRG1) in pulmonary fibrosis is unknown, but it was reported that SCRG1 is associated with the stemness of MSCs." (PMID 36726784, 2022). "Thus, in vitro and in vivo experiments are needed to confirm whether IL-17-producing cells are the targets of HGF and whether IGFBP5 and SCRG1 participate in the treatment of pulmonary fibrosis." (PMID 36726784, 2022).
synovitis (1 paper, 2022). Inflammation of a synovial membrane. "SCRG1, as a diagnostic marker of OA, may be significantly up-regulated by hsa-miR-363-3p in synovitis of OA, and co-regulate immune-related pathways through the interaction of related proteins, playing an important role in the occurrence and development of OA, which may be a new drug target." (PMID 35720295, 2022). "As a reliable biomarker and therapeutic target for OA synovitis, the extent to which SCRG1 upregulated promotes the development of OA in synovitis and the corresponding function remains to be studied." (PMID 35720295, 2022). "miRNA hsa-miR-363-3p plays an important role in regulating SCRG1 in OA synovitis." (PMID 35720295, 2022). "While the data used in the analysis were not representative of BST1 gene expression in specific cell types of OA synovitis, the single-cell sequencing may help us to understand the role of SCRG1 in cell communication." (PMID 35720295, 2022).
tumour (7 papers, 2018 to 2024). "When we integrated several of these genes into a multivariate LASSO regression model to define poor tumour outcome in the BX‐Neu+ mouse cohort, four genes were identified that were associated with poor survival in BX‐Neu+ mice: Oip5, Higd1a, Shc4 and Scrg1." (PMID 38344872, 2024). "Immunostaining of human tumor tissues confirmed that SCRG1-positive dCAFs co-localized with the malignant epithelium during early stages of tumor development, and were present in the epithelium as well as fibrous stroma of more advanced tumors." (PMID 33906694, 2021). "dCAFs, as identified by the specific marker SCRG1, were scarce in tumor tissue from MMTV-PyMT mice, in agreement with the low number of cells from this subtype that were isolated from the original tumors." (PMID 30514914, 2018). "Conversely, dCAFs originated from tumour epithelium that has undergone an EMT and therefore highly expressed genes associated with cell differentiation and morphogenesis [i.e., scrapie responsive gene 1 (SCRG1), SRY-box transcription factor 9 and 10 (SOX9 and SOX10)]." (PMID 33066013, 2020). "Indeed, simultaneous detection of the vCAF marker Nidogen-2, the mCAF marker PDGFRα, and the dCAF marker SCRG1, identified three distinct stromal populations with divergent growth patterns and localization in relation to the nests of tumor cells." (PMID 30514914, 2018). "Additionally, SCRG1-positive dCAFs were located on the tumor-stroma boundary, suggestive of their putative origin as malignant epithelial cells." (PMID 30514914, 2018). "Interestingly, dCAFs were intermingled with the malignant epithelium during early stages of tumor development, whereas SCRG1-positive cells could be found both within the epithelium and in stromal streaks of late-stage tumors." (PMID 30514914, 2018). "In total, five populations were designated tumour clusters, which had various features: (TumourC0) CD74 and APOD; (TumourC1) IF16, JUN and HSPA1A; (TumourC2) S100B and SCRG1; (TumourC3) NEAT1 and MALAT1; and (TumourC4) WFDC2 and RNASE1 (HLA‐DRA, CD68, CD3D, CD3E)." (PMID 37784253, 2023).
infection (2 papers, 2013 to 2022). The state of being infected such as from the introduction of a foreign agent such as serum, vaccine, antigenic substance or organism. "Further analyses at day 140 post-infection uncovered only 3 additional upregulated genes (SCRG1, LY86, SFT2D2) in IFNR−/− mice." (PMID 23737750, 2013). "Scrapie responsive gene 1 (SCRG1) is predominantly expressed in neurons and is overexpressed in the central nervous system during infection or brain injury." (PMID 36241983, 2022).
SCRG1 also shares sentences with these, for which no sentence is quoted: cancer (1 paper); Cirrhosis (1); hepatocellular carcinoma (1); liver cancer (1); liver cirrhosis (1); prion disease (1); schizophrenia (1); sporadic CJD (1).